IL1B (interleukin 1 beta)
Diseases named in the same sentence as IL1B in open-access papers (continued):
Sharing a sentence is not in itself a finding about the gene and the disease.
depression (continued). "Interestingly, central administration of IL-1β decreased nocturnal melatonin secretion in sheep, which could suggest a link between inflammation, depression and sleep disturbances." (PMID 33255237, 2020). "Furthermore, previous studies have shown that ketamine could alleviate LPS-induced depression-like behaviors, which were related to increased expressions of IL-1β and IL-6 and decreased expression of IL-10 in the rats." (PMID 32522211, 2020). "Moreover, related research on NLRP3 inflammasomes and P2X7 receptors is summarized and used as a reference for confirming that the excessive activation of P2X7- NLRP3 leads to the increased release of inflammatory cytokines, such as IL-1β, in depression and diabetes." (PMID 32166013, 2020). "In line with our expectations, the levels of the pro-inflammatory cytokines TNF-α, IL-1β, and IL-6 were decreased after the ketamine infusions in our study, which is consistent with the results of previous studies that administered a single infusion in patients with depression." (PMID 32699226, 2020). "Some meta-analyses do not find an overall association between IL-1β and major depression, although it was suggested that this could be due to measurement issues as concentrations of IL-1β are very low in blood." (PMID 30967802, 2019). "However, others have reported elevated IL-1β levels in major depression, and a separate meta-analysis found elevated IL-1β in patients affected with major depressive disorder, although, this was only when the studies included were rated as having high quality methodologies." (PMID 30967802, 2019). "However, whether IL-1β up-regulates p38 phosphorylation and thus triggers neuronal apoptosis to promote depression-like behaviors in the chronic unpredictable mild stress (CUMS)-induced animal model requires further investigation." (PMID 30666189, 2018). "Studies have shown that Il-1β may be involved in the pathophysiological process of depression, and the response to antidepressant treatment involves reducing the function of the 5-HT system, activating the hypothalamic-pituitary-adrenal (HPA) axis, and affecting the regeneration of neurons." (PMID 29736181, 2018). "Moreover, Maes and fellow workers have established an association between the presence of functional SNPs in TNF-α, IL-1β and CRP and an increased risk of developing depression and, indeed, responsiveness or otherwise to the administration of antidepressant therapy." (PMID 29294244, 2018). "Interestingly, higher serum levels of IL-1β and IL-6 may accout for ketamine’s antidepressant effect in the rat with depression-like phenotype after SNI." (PMID 28600519, 2017). "Furthermore, these findings from this study demonstrate a complex relationship between fluoxetine and its effect on levels of different pro-inflammatory cytokines in treating depression, whereby it has a greater ability to significantly reduce plasma and brain IL-1β levels in a rat model of CMS." (PMID 29049348, 2017). "Furthermore, serum levels of IL-1β and IL-6 at baseline may predict ketamine’s antidepressant effects in pain-induced depression." (PMID 28600519, 2017). "In addition, it seems that NLRP3 inflammasome and IL-1β also play pivotal roles in depression." (PMID 29084550, 2017). "Intense cardiovascular exercise has been shown to elicit generalized fatigue and depression associated with changes in the expression of neurotransmitters such as glutamine, dopamine and 5-HTP and the production of large quantities of proinflammatory cytokines such as IL-1β, IL-6 and TNF- α." (PMID 28360847, 2017). "Furthermore, ketamine could decrease serum levels of IL-1β and IL-6 in rats with depression-like phenotype compared with saline treatment (P < 0.05)." (PMID 28600519, 2017).
depression (continued). "The monocyte-T-lymphocyte theory of depression, devised by Smith and Maes in the early 1990s, proposes that increased proinflammatory cytokine secretion in the form of IL-1β, TNF-α, and IFN-γ is responsible for the initiation and maintenance of a depressive episode." (PMID 26775294, 2016). "Thus, stress via enhanced release of pro-inflammatory cytokines such as TNF-α, IL-1β and IL-6 may not only precipitate depression, but may also accelerate the neurodegenerative processes." (PMID 25514226, 2014). "However, it seems that HPA axis and sympathetic nervous system activity, as well as that of circulating IL-1β and IL-6, may vary greatly in individuals with typical vs. atypical features of major depression." (PMID 25565946, 2014). "The results showed that the mRNA levels of IL‐1β, iNOS, IL‐6, and TNF‐α were increased in the brain of depression model mice, and all of them were down‐regulated in the DSCG‐treated depression model mice." (PMID 41556446, 2026). "In this study, compared to the control group, CRS mice with anxiety and depression showed significantly increased expression levels of Notch1/Hes-1, TNF-α, IL-1β, and IL-6 in the hippocampal region." (PMID 39789446, 2025). "In mice models exposed to chronic unpredictable stress, an increased expression of cytokines IL-1β, IL-6, and TNF-α in the amygdala was observed and mice presented symptoms of depression and anxiety disorder." (PMID 40141110, 2025). "In a murine LPS-induced depression model, the MAOI tranylcypromine was shown to reduce the expression of pro-inflammatory cytokines IL-1β, IL-6, and TNF-α." (PMID 40277932, 2025). "In a model of depression, zileuton significantly improved depressive‐like behavior by suppressing hippocampal TNF α, IL-1β, nuclear NF-κB p65 and microglial activation, reducing neuronal apoptosis and restoring synaptic proteins and neurogenesis." (PMID 40538546, 2025). "Next, we examined social and depression-like phenotype and the expression of pro-inflammatory markers (TNF-α, IL-1β, NF-κB1, and IL-6) in the ventromedial prefrontal cortex (vmPFC) and hippocampal CA1 brain regions." (PMID 40558565, 2025). "qPCR results showed that knockdown of Homer1 improved the expression of inflammation‐related markers IL‐1β, TNF‐α, IL‐10, and depression‐related markers ERCCL2, SLC6A4, and GAD1 in primary neurons, both in the PTSD group and in the TBI+Hcort group." (PMID 39665190, 2025). "Enhanced levels of neuroinflammatory cytokines (such as IL-1β, TNF-α, and IL-6) are observed in individuals with depression." (PMID 40703750, 2025). "In rodent models of depression induced by chronic unpredictable stress, expressions of TNF, IL-1β, IL-6, cyclooxygenase-2 (COX-2), and inducible nitric oxide synthase (iNOS) are elevated in the hippocampus." (PMID 40710585, 2025). "C3, which shows a positive correlation with TNF-α, IL-6, and IL-1β, can suppress inflammation in the context of CSVD with depression." (PMID 40584618, 2025). "Escitalopram can reduce the levels of pro-inflammatory cytokines—IL-1β, IL-1ra, IL-2, IL-4, IL-6, IL-8, IFN-y, TNF-α in the serum of patients suffering from depression, while simultaneously increasing the level of anti-inflammatory IL-10." (PMID 41302150, 2025). "In depression, rats exposed to CUMS exhibit upregulation of the P2X7R/NLRP3/IL-1β signaling axis and display depression-like behaviors." (PMID 40936908, 2025). "The level of interleukin (IL)-1β, IL-6, tumor necrosis factor α (TNF-α), and depression-like behavior in rats showed that the CP/CPPS complicated with depression model was established successfully." (PMID 40576719, 2025). "Its root extract suppresses the expression of inflammation-related proteins such as cyclooxygenase-2, iNOS, IL-6, IL-1β, and TNF-α, while modulating neuroendocrine and neurotransmitter systems to exert neuroprotective effects in mouse models of depression." (PMID 40936908, 2025).
depression (continued). "The model group exhibited significantly higher levels of IL-1β, IL-6, and TNF-α compared to the blank group (p < 0.01), indicating that the depression model successfully induced systemic inflammatory responses." (PMID 41464995, 2025). "Cumulative studies have demonstrated peripheral proinflammatory markers, such as CRP, IL-6, IL-1β, and TNF-α, were significantly increased in individuals suffering from depression." (PMID 40108901, 2025). "There were also trends observed for genetic variations in IL1β and IL2 and their interactions with child adversity and depression." (PMID 41009999, 2025). "Clinical and research data have reported that inflammatory markers in both the blood and the brain, including interleukin IL-1β, IL-6, and tumor necrosis factor TNF-α, are markedly elevated in individuals with major depression." (PMID 40006068, 2025). "Increased levels of inflammatory mediators, such as cytokines like IL-1β, TNF-α, and IL-6, are often seen in patients who suffer from severe depression." (PMID 40574754, 2025). "Recent research has revealed a crucial role for pro-inflammatory cytokines, including interleukin (IL)-1β, IL-6, and tumor necrosis factor (TNF)-α, in stress-induced depression." (PMID 40612748, 2025). "Mice undergoing oophorectomy experience a decrease in estrogen levels, leading to an increase in P2X7R expression, and IL-1β,IL-18,NLRP3 inflammasome activation leads to hippocampal neuroinflammation and depression." (PMID 38642324, 2025). "The anti-inflammatory activity of omentin resides in its ability to downregulate the production of IL-1β, IL-6, and TNF-α, which are often involved in depression’s pathogenesis." (PMID 41375608, 2025). "Our study's strength lies in the inclusion of a comparison group and the estimation of serum BDNF and IL-1β levels in conjunction with HDRS scores, which provide a more robust assessment of depression severity." (PMID 40904969, 2025). "Other studies have shown significant associations between various serum biomarkers—IL-2, IL-6, IL-10, IL1-B, TNF-α, CRP, CRH, and cortisol—and pregnancy-specific anxiety and depression across all trimesters of gestation." (PMID 40565847, 2025). "Concurrently, inflammatory cytokines like IL-1β and TNF-α induce serine phosphorylation of insulin receptor substrates, establishing a molecular bridge between inflammation, depression, and metabolic dysfunction." (PMID 40904459, 2025). "One of the key findings of this study was the significant elevation of pro-inflammatory cytokines—interleukin-1β (IL-1β) and tumor necrosis factor-α (TNF-α)—in the depression subgroup." (PMID 40823578, 2025). "One previous study reported that expression of IL-1β was increased as well as IL-6 and TNF-α in PFC of the teenage suicide depression patients, consistent with peripheral findings." (PMID 40179065, 2025). "Hence, IL-1β signaling may be a possible bridge mechanism between Akt/mTOR/NF-κB-mediated microglial hyperactivation and neurogenesis impairment in DG seen in mice model of depression." (PMID 40011631, 2025). "It is understood that the maturation of IL-1β, which involves the cleavage of Caspase-1, relies on the NLRP3 inflammasome and significantly impacts depression." (PMID 40308754, 2025). "Meta-analysis showed that IL-1β was significantly lower in the test group than in the control group (SMD: −1.62, 95% CI: −1.93, −1.31), indicating that depression animals treated with acupuncture had significantly lower levels of IL-1β (P<0.05)." (PMID 41244868, 2025). "Inflammatory markers such as IL-1β, IL-6, TNF-α, IL-18, and CRP are commonly observed in animal models of depression." (PMID 40277932, 2025). "Most present studies mainly focused on exploring the relationship of IL-1b, IL-2, IL-6, and TNF-a, with depression." (PMID 40530060, 2025). "In HFD-induced depression models, the expression of NLRP3, ASC, caspase-1, and IL-1β is markedly elevated." (PMID 41194915, 2025).
depression (continued). "Increased evidence points to the number of immune-related genes, such as IL1B, IL6, and TNF, that connect epilepsy and depression through inflammatory pathways." (PMID 40941042, 2025). "A growing amount of data indicates that the overproduction of pro-inflammatory cytokines, such as IL-1β, IL-6, and TNF-α, by immune cells within the brain, plays an important role in the onset and progression of depression." (PMID 40612748, 2025). "Pro-inflammatory proteins identified include TNF-α, IL-6, IL-1β and C-reactive protein (CRP) which have been found to be increased in individuals with depression." (PMID 39867847, 2025). "This stands in line with information from Smith’s macrophage theory of depression in which he identified, in addition to il-1β, IFN-α, and TNF-α among the main substances that can provoke and influence the course of depression." (PMID 40004649, 2025). "Once activated, it promotes the release of proinflammatory cytokines (IL-1β, IL-18), impacting neuronal and glial function and potentially contributing to conditions such as PTSD and depression." (PMID 41008651, 2025). "Carvacrol, a monoterpene found in the essential oils of aromatic plants such as Origanum vulgaris and Thymus vulgaris, reduces oxidative stress and decreases hippocampal IL-1β and TNF-α levels, thereby improving depression-like behavior induced by CUMS." (PMID 40936908, 2025). "In rats with CSVD and depression, PY significantly increased body weight; alleviated depression-like behaviors; and decreased the levels of inflammatory cytokines such as TNF-α, IL-1β, and IL-6 in both serum and hippocampus." (PMID 40584618, 2025). "Wendan decoction effectively reduced the levels of pro-inflammatory factors IL-1β, IL-6, and TNF-α, with similar anti-inflammatory effects reported in depression treatment, underscoring its multimodal therapeutic action." (PMID 40713709, 2025). "Both preclinical and clinical studies have found higher levels of IL-1β, TNF-α, and IL-6 in peripheral blood and brain tissue of patients with depression." (PMID 41561993, 2025). "In this model, compared to the control cells, the levels of 5‐HT and GABA were significantly lower, while TNF‐α, IL‐1β, and IL‐6 levels were markedly higher in the CORT‐induced depression cell model." (PMID 40491976, 2025). "At the end of the experimental procedure, MDA, GSH, BDNF, IL‐1B, and NLRP3 levels were analyzed in the hippocampus to analyze the physiopathological mechanism of menopause‐related depression and the therapeutic effects of valsartan on these mechanisms." (PMID 39443283, 2024). "Central infusion of pro-inflammatory cytokines such as IL-1β and interferon-α (INF-α) can induce depression-like behaviors in animals." (PMID 39130643, 2024). "Considering this information, our study observes that the physiopathology of depression‐like behavior after ovariectomy includes an increase in NLRP3 and IL‐1β levels and a decrease in BDNF levels in the hippocampal area." (PMID 39443283, 2024). "The objective of this research is to explore the impact of AT1RB therapy on depression and anxiety‐like behaviors triggered by menopause, as well as the levels of NLRP3, IL‐1β, BDNF, and oxidative stress in the hippocampal and prefrontal cortex tissues." (PMID 39443283, 2024). "The clinical study has reported that elevated levels of pro-inflammatory cytokines IL-1β, IL-6, and TNF-α are observed in depression patients, accompanied by the activation of microglia in the central nervous system." (PMID 38643466, 2024).
depression (continued). "For example, the release of cytokines such as IL-12p70, TNF-α, IL-1β, IL-8, IL-6, and interferon-γ (IFN-γ) leads to CSC, including cancer-related fatigue (CRF), sleep disturbances, pain, anxiety, and depression." (PMID 38745774, 2024). "Pro-inflammatory factors such as interleukin-1β (IL-1β), interleukin-6 (IL-6), and tumor necrosis factor-alpha (TNF-α) are regarded as depression biomarkers." (PMID 38389919, 2024). "Consistent with our findings, activation of the NLRP3 inflammasome was observed in AMI rats with depression, leading to the cleavage of GSDMD and subsequent release of IL‐18 and IL‐1β, thereby promoting microglial pyroptosis." (PMID 38970230, 2024). "Our results are consistent with previous clinical studies, which showed that IL-1β, IL-6, and TNF-α levels were increased in patients with depression." (PMID 39498265, 2024). "US-exposed mice treated with vehicle exhibited decreased sucrose preference, a sign of anhedonia, a key feature of depression, increased anxiety-like behavior, elevated corticosterone levels, and enhanced TNF and IL-1β gene expression in the brain." (PMID 38912378, 2024). "The effectiveness of the treatment was evaluated by the Hamilton Depression Scale (HAMD-17), Self-Depression Scale (SDS), Modified Barthel Index Score (MBI), and the serum levels of IL-1β, IL-6, IL-10, TNF-α, and INF-γ." (PMID 38370556, 2024). "Numerous studies have shown that inflammatory mediators and cytokines such as interleukin-1β (IL-1β), interleukin-6 (IL-6), and tumor necrosis factor-α (TNF-α) are frequently present in the peripheral blood of patients with depression." (PMID 39114351, 2024). "Studies have found that acupuncture at GV20 and EX-HN3 can regulate the levels of cytokines such as IL-1β and IL-6 in the hippocampus and PFC, thereby inhibiting inflammatory responses to alleviate depression." (PMID 39367470, 2024). "Recent evidence suggests that neuroinflammation is a key mediator of depression, and, in particular, the expression of pro-inflammatory factors such as NLRP3 and IL-1β is significantly enhanced in depressed patients." (PMID 39770545, 2024). "Previous studies have consistently observed elevated levels of pro-inflammatory cytokines such as interleukin-1β (IL-1β), IL-6, and tumor necrosis factor-α (TNF-α) in the blood of patients with depression." (PMID 39130643, 2024). "Ferulic acid inhibited the activation of microglia and significantly decreased the contents of IL-1β, IL-6, and TNF-α in the prefrontal cortex of the CUMS-induced depression mouse model by inhibiting the NLRP3/caspase-1/NF-κB pathway." (PMID 38915473, 2024). "Acupuncture prevented CUMS-induced depression-like behaviors by reversing the hyper-activation of the HMGB1/TLR4 signaling pathway and by downregulating IL-1β, TNF-α, and IL-6 in the amygdala (AMY) and blood of rats." (PMID 38791125, 2024). "Pathological studies have observed increased expression of TNF-α, IL, IL-1β, IL-6, and C-X3-C modality chemokine receptor 1 (CX3CR1) in the brain of patients with depression." (PMID 39654612, 2024). "It has been shown that pro-inflammatory cytokines such as interleukin-1β (IL-1β) and tumor necrosis factor (TNF) can activate systemic inflammatory responses, directly or indirectly mediating the onset of depression." (PMID 39367470, 2024). "For example, researchers have indicated that peripheral blood interleukin-1β (IL-1β), IL-6, tumor necrosis factor-α (TNF-α), and C-reactive protein are the most reliable biomarkers of inflammation in patients with depression." (PMID 38745774, 2024). "Several studies have reported that patients with depression exhibit significantly elevated levels of pro‐inflammatory cytokines, including TNF‐α, IL‐1β, and IL‐6." (PMID 39554370, 2024). "In conclusion, this study identified significant differences in serum BDNF, GDNF, 5-HT, and IL-1β among the HC, PWE, and PWECD groups, suggesting their involvement in epilepsy and comorbid depression." (PMID 39474368, 2024).